INS (insulin)
Diseases named in the same sentence as INS in open-access papers (continued):
Sharing a sentence is not in itself a finding about the gene and the disease.
macrosomia (continued). "First, results from the HAPO study showed that outcomes of macrosomia, cesarean delivery, and increased cord insulin levels increased with each stepwise increase in glucose recorded after the administration of a 75-gram 2-hour glucose tolerance test." (PMID 31886283, 2019). "In the pairwise meta-analysis, we observed that metformin had lower incidence of macrosomia compared with insulin (RR, 0.68; 95% CI, 0.55 to 0.86; P < 0.05)." (PMID 31781670, 2019). "The incidence of macrosomia was 12% in the group requiring metformin only and 15% in the group with metformin plus insulin and only 5% in patients on insulin only." (PMID 29970197, 2018). "There was a tendency to have higher insulin concentrations in fetal macrosomia, compared to newborns with normal birth weight (P = 0.086)." (PMID 29137266, 2017). "The fetuses of treated groups showed macrosomia (p <0.05 compared to control), corroborating to other comparative studies with insulin and GLIB, which also showed macrosomia for GLIB." (PMID 26623340, 2014). "There is one report that infants born of overweight women and obese GDM women, who achieved glycemic control with insulin exhibited comparable rates of macrosomia as infants of normal weight GDM women." (PMID 25302493, 2014). "It was observed that, on the day of birth, the rat newborns of diabetic dams presented elevated plasma insulin and macrosomia." (PMID 23878822, 2013). "The pups born to the mild diabetic dams had higher birth weight (macrosomia), pancreatic insulin content, plasma insulin, and C-peptide concentrations compared to those pups born to control dams." (PMID 23878822, 2013). "This concept was based on studies reporting that macrosomia occurs as a result of fetal insulin hypersecretion in response to the mother rise of glycemia." (PMID 22110473, 2011). "Earlier studies from pregnant diabetic women treated with animal insulin, however, noted that some offspring with macrosomia also had animal insulin in their cord blood." (PMID 19956710, 2009). "Compared with insulin, metformin demonstrated a significant reduction in the risks of pre-eclampsia (RR 0.61), induction of labor (RR 0.90), CD (RR 0.91), macrosomia (RR 0.67), NICU admission (RR 0.75), neonatal hypoglycemia (RR 0.55), and LGA infants (RR 0.80, 95% CI 0.68 to 0.94, p = 0.007)." (PMID 39860070, 2025). "Elevated plasma insulin may inhibit fatty acid oxidation, and impaired triglyceride oxidation triglycerides may contribute to macrosomia." (PMID 40218968, 2025). "Although there is evidence of biomarkers associated with the insulin pathway, some researchers challenge the view that the insulin signaling pathway is the primary factor in macrosomia development and instead propose alternative mechanisms for fetal growth in GDM and normoglycemic mothers." (PMID 40362828, 2025). "Additionally, circulating FFAs in maternal blood, which pass through the placenta, contribute to the development of insulin resistance and fetal macrosomia." (PMID 40362828, 2025). "The insulin usage rate in the GDM with macrosomia group was significantly higher." (PMID 40797060, 2025). "The elevated risk of developing any complications, gestational hypertension, pre-eclampsia, maternal insulin use, primary Caesarean section, shoulder dystocia, macrosomia, and LGA occurred in levels below the current recommended diagnostic cut-off of FG 5.1 mmol/L (category 7)." (PMID 39448754, 2024). "Furthermore, we analysed other pregnancy outcomes, and increased risks of maternal insulin use and macrosomia were observed with both FG and 2 hG in our cohort." (PMID 39448754, 2024). "Finally, despite no study in this systematic review showing statistical significance, the treatment of GDM with metformin appears to be safe and effective regarding fetal macrosomia and with better outcomes compared to insulin therapy." (PMID 39669300, 2024).
macrosomia (continued). "The MiTy study reported a statistically significant reduction in birth weight, elevation in the rate of SGA and reduction in the rate of macrosomia in offspring exposed to insulin and metformin combined, compared to insulin with placebo (p = 0.0016, p = 0.026, p = 0.046 respectively)." (PMID 37798604, 2024). "Some studies suggest that metformin does not increase the risk of fetal macrosomia (excessive fetal growth) or preterm birth compared with insulin therapy, although there are mixed results in the literature." (PMID 39683486, 2024). "However, an early HbA1c level of ≥5.7% indicated increased risks of using maternal insulin, macrosomia, and shoulder dystocia." (PMID 38362048, 2024). "Insulin acts as a growth factor for the fetus, leading to macrosomia and LGA." (PMID 39125293, 2024). "The risk of macrosomia is substantially lower (by 30%) when GDM is treated with metformin than with insulin, and there is no concomitant increase in the risk of being born SGA or LGA." (PMID 36593391, 2023). "For example, Metformin-exposed neonates are lighter, have reduced lean mass and lower risk of macrosomia than insulin-exposed neonates, independent of maternal glycaemic control." (PMID 38288471, 2023). "However, if fasting plasma glucose levels are between 108 and 125 mg/dL and there are concomitant polyhydramnios or fetal macrosomia, insulin is also recommended for use right from the start." (PMID 37765126, 2023). "An Iranian study discovered that even minor changes in blood glucose levels can result in macrosomia (abnormal fetal growth) and other complications, which can be avoided by implementing simple measures such as a controlled diet and insulin use during the gestational period." (PMID 36938248, 2023). "Thus, the combinative effect of extra glucose and insulin leads to the increased accumulation of adipose tissue and protein in the fetuses, resulting in fetal accelerated growth and macrosomia." (PMID 35222271, 2022). "It provides an association of IGF-1 and Insulin with fetal macrosomia in a largely non-diabetic population of pregnant women." (PMID 36001625, 2022). "Given the anti-inflammatory and insulin sensitizing effects of n-3 PUFA, RCTs in these higher risk women are therefore needed to evaluate the role of n-3 PUFA in preventing intrauterine growth restriction and macrosomia." (PMID 33572368, 2021). "Yet, retrospective observational studies have shown that fetal genotype, not maternal treatment with insulin, is the main determinant of fetal growth and of the risk of macrosomia." (PMID 35069449, 2021). "In pregnant women with impaired carbohydrate metabolism, there may be, for example, increased placental transport of nutrients with increased insulin resistance and, consequently, foetal macrosomia." (PMID 34371854, 2021). "Gestational age at initiation of insulin therapy was also highly variable (from pre-conceptual to 38 weeks of gestation), while it has been suggested that early normalization of maternal blood glucose is necessary to prevent macrosomia reviewed in." (PMID 35069449, 2021). "Given that the most common fetal consequence of maternal metabolic disease is macrosomia predominately due to excess fat mass, later life insulin resistance may arise from a perturbation in adipose tissue development." (PMID 34459218, 2021). "The results of our net-work meta-analysis suggested that metformin be the most promising intervention to reduce the incidence of neonatal hypoglycemia, LGA, macrosomia, hyperbilirubinemia, anomaly and perinatal death, while insulin and glyburide ranking second and third." (PMID 34641848, 2021). "US allowed to identify the infants at low risk of macrosomia, and to avoid insulin therapy in their mothers, with no increase of pregnancy adverse outcomes, particularly no increase of LGA, nor of small for gestational age offspring." (PMID 35069449, 2021).
macrosomia (continued). "Although it is currently recommended to institute insulin therapy in GCK-MODY women whose babies are at high risk of macrosomia, this strategy has not been implemented in routine practice." (PMID 35069449, 2021). "If our amniotic fluid samples had been collected in the third trimester of pregnancy, insulin measurements would have been expected to reflect fetal growth velocity, as insulin and insulin-related molecules constitute the dominant growth-promoting factors of macrosomia during late gestation." (PMID 34564397, 2021). "The antenatal use of vitamin D containing supplements in non-insulin treated GDM patients might reduce the risk of CS and macrosomia." (PMID 32517428, 2020). "In our study, insulin therapy, gestational age at its institution, and insulin doses were not independently associated with an increased risk of macrosomia and/or shoulder dystocia." (PMID 32346630, 2020). "In keeping with the overall lower birth weight in the metformin-exposed group, macrosomia was lower by 40% compared to the insulin-exposed group (OR 0.59, 95% CI 0.46 to 0.77, I2 = 0%, p < 0.001), although this result may be influenced by publication bias." (PMID 31386659, 2019). "But may also be due to differences related to GDM including more estimated macrosomia on ultrasound, worse glycaemic control indicated by significantly more insulin therapy." (PMID 29747601, 2018). "Indeed, there is good evidence that timely diagnosis and treatment of GDM by dietary advice, blood glucose monitoring, and insulin therapy when needed significantly reduce perinatal complications such as preeclampsia or macrosomia." (PMID 30693288, 2018). "Moreover, metformin (plus insulin when required) ranked the best with the lowest incidence of macrosomia, PIH, LGA, RDS." (PMID 28930827, 2017). "Direct consequences might include increased glucose flux into the fetal circulation, intensified fetal growth and the subsequent macrosomia, which in the present study was more common in the insulin-dependent diabetic groups." (PMID 27981520, 2017). "In addition, macrosomia occurred significantly more often when the mothers received glyburide than when the mothers received insulin." (PMID 28771572, 2017). "Moreover, most of the fetuses presented macrosomia and high levels of plasma glucose and insulin at first day of life." (PMID 23878822, 2013). "Additionally, elevated triglycerides and amino acids may contribute to fetal macrosomia by stimulating the secretion of insulin and other growth factors." (PMID 39683486, 2024). "However, our study found that women with an HbA1c level of ≥5.7% before 24 weeks of gestation had significantly higher risks of pregnancy and neonatal complications, including the need for insulin to optimize maternal glycemic control and the incidences of macrosomia and shoulder dystocia." (PMID 38362048, 2024). "We found that neonatal-onset patients with KATP variants were prone to be macrosomia at birth, presented with milder symptoms and had a higher percentage of operative intervention, along with higher levels of serum insulin and C-peptide than non-neonatal onset ones." (PMID 40302972, 2024). "Recent studies and meta-analyses have shown higher prevalences of neonatal complications, mainly macrosomia and neonatal hypoglycemia, in users of glyburide, and higher prevalences of preterm birth and preeclampsia in users of metformin, compared with users of insulin." (PMID 34641848, 2021). "As regards insulin therapy, three observational studies suggested that GDM treatment with insulin, compared to nutritional therapy alone, may be associated with a poorer prognosis, including a higher rate of macrosomia." (PMID 32346630, 2020).
macrosomia (continued). "In this regard, our present observations suggest that macrosomia in offspring resulting from the exposure to high maternal glucose and insulin concentrations may involve the excessive growth of skeletal muscle, due to increased number of myoblasts contributing to the formation of muscle fibers." (PMID 24615360, 2014). "While rates of macrosomia and NICU admission were higher in the insulin group (32.5% and 27.5%, respectively), these differences were not statistically significant." (PMID 40672007, 2025). "The purpose of this study was to assess the relationship between fetal insulin, insulin-like Growth factor-1(IGF-1), and macrosomia in a resource-limited setting." (PMID 36001625, 2022). "Several authors have reported the role of insulin, IGF-1, and glucose in the determination of birth size, and by extension, fetal macrosomia in addition to fetal anthropometry." (PMID 36001625, 2022). "Fetal macrosomia is common in pregnancies with GDM; this is mainly due to the increased insulin resistance of the mother." (PMID 35626396, 2022). "Currently, to understand the role of insulin on GDM pathophysiology and fetal macrosomia is a challenge." (PMID 28587267, 2017). "A meta-analysis supported these findings, showing no improvement in fasting blood glucose, insulin requirements, birth weight, caesarean delivery rates, macrosomia, or the incidence of LGA or SGA infants with a low-carbohydrate diet initiated at 29–31 weeks." (PMID 40218968, 2025). "An older age, history of GDM or macrosomia, high pre-pregnancy BMI, gestational age at the diagnosis of GDM, insulin therapy during pregnancy, high HbA1c (>5.25%), delivery by cesarean section, and macrosomia were linked to postpartum glucose tolerance disorders." (PMID 38618305, 2024). "Insulin initiation in the third trimester in this context has not been proven to prevent macrosomia." (PMID 38933924, 2024). "An AC disproportionately greater than the 75th percentile suggests the foetus is a non-carrier and insulin is needed to prevent macrosomia and delivery should occur at 38 weeks." (PMID 38933924, 2024). "Although there were no significant statistical differences, pregnant women with insulin-treated T2DM seemed to have a relatively lower incidence of macrosomia and less GWG." (PMID 36339424, 2022). "At this stage, insulin and IGF-1 act as growth factors on fetuses resulting in macrosomia." (PMID 32708537, 2020). "The risk of macrosomia is substantially lower, by 40%, when GDM is treated with metformin compared to insulin, without a concomitant increase in the risk of being born SGA." (PMID 31386659, 2019). "Current study also shows that LGA newborns had significantly higher cord serum C-peptide levels in addition to higher leptin and insulin levels than AGA newborns, which is consistent with previous studies revealing that C-peptide levels in macrosomia were significantly higher than in AGA infants." (PMID 31975995, 2019). "There is no consensus on the timing of initiation of insulin therapy, but there are more conservative guidelines for reducing macrosomia and related risks in the fetus." (PMID 30820209, 2018). "The risks of Caesarean section, delivery before 37 weeks and macrosomia were higher in the insulin-treated GDM group than in the non-insulin-treated GDM group." (PMID 28197657, 2017). "Also a positive correlation between serum insulin levels and HOMA-IR in GDM subjects and macrosomia was observed, as well as between maternal serum TG levels and macrosomia." (PMID 24639763, 2013). "However the macronutrient metabolism cannot completely explain the relationship between maternal metabolic conditions and macrosomia, because lifestyle modification or maternal insulin adjustment does not always reduce the incidence of macrosomia." (PMID 38894719, 2024).
macrosomia (continued). "Macrosomia prevalence irrespective of definition was higher in the insulin-treated group, but diet-treated women had a rate of 6.3% macrosomia based on the Swedish clinically used definition of 4500 g, compared with 3.8% in the background population and 9.8% in the insulin-treated group." (PMID 36014870, 2022). "There were differences in BMI, haemoglobin A1c, fasting blood glucose, 1-h postprandial glucose (PG), 2-h PG, insulin levels, triglycerides,weight gain during pregnancy, the rate of macrosomia, fetus birth weight and PROM between women with and without GDM (all P < 0.05)." (PMID 33957911, 2021). "Furthermore, the prevalence of macrosomia was higher in the glyburide group than in the insulin group (RD 0.04; 95% CI 0, 0.08), but the difference was not significant (p = 0.07)." (PMID 34641848, 2021). "Thus, the correlations between specific OTUs/phyla/genera and cord blood insulin, IGF-1 and leptin level may help to explain their roles in the development of fetal macrosomia." (PMID 29137266, 2017). "For KATP subgroup, neonatal-onset patients tended to be macrosomia, had a higher birth weight, inclined towards milder symptoms at onset, exhibited a higher proportion of surgical intervention, and had higher concentrations of serum insulin and C-peptide than those with non-neonatal onset." (PMID 40302972, 2024). "In addition, it may influence macrosomia as appropriate management of GD with nutritional therapy and insulin if not well controlled with diet alone has been reported to reduce its rates." (PMID 33224106, 2020). "In addition, the prevalence of macrosomia and/or LGA infants was no different from women who used NPH insulin in pregnancy." (PMID 18959615, 2008). "Finally, in studies not reporting the use of insulin, GDM pregnancies had increased odds of congenital malformations (1.18; 1.10-1.26), preterm delivery (1.51; 1.19-1.93), macrosomia (1.48; 1.13-1.95), neonatal hypoglycemia (11.71;7.49-18.30), and admission to NICU (2.28; 1.26-4.13)." (PMID 39389786, 2024). "As one retrospective report pointed out, overweight pregnant PCOS patients developed significantly higher fasting insulin levels compared to lean PCOS patients and significantly higher rates of macrosomia could be observed in overweight but not lean PCOS patients." (PMID 33374430, 2020).